SPP1 (secreted phosphoprotein 1)
Diseases named in the same sentence as SPP1 in open-access papers (continued):
Sharing a sentence is not in itself a finding about the gene and the disease.
ovarian carcinoma (continued). "Previous studies have demonstrated that SPP1 is overexpressed in a variety of cancers and can be used to predict chemotherapy prognosis, such as ovarian cancer, glioblastoma, HCC and gastric cancer." (PMID 36225568, 2022). "To gain more detailed insights into the potential immune functions of SPP1 in ovarian cancer and its regulatory network, we performed the bioinformatics analysis of public data to guide future research in ovarian cancer." (PMID 36585688, 2022). "We found that SPP1 existed in both cell cytoplasm and membrane, and about 35.3% (132/373) ovarian cancer patients with SPP1 high expression." (PMID 36585688, 2022). "The macrophage state that expresses secreted phosphoprotein 1 (SPP1) promotes vascular production of M2-related genes and is identified in a variety of tumor types, including lung, colorectal, and ovarian cancers as well as pancreatic adenocarcinoma." (PMID 36362044, 2022). "The impact of SPP1 expression level on the clinical outcome of ovarian cancer patients were evaluated via Kaplan–Meier Plotter and PrognoScan dataset." (PMID 36585688, 2022). "We first evaluated the expression of SPP1 in ovarian cancer and normal ovary tissue using GEPIA database." (PMID 36585688, 2022). "Next, we assessed the correlations between SPP1 expression and immunoinhibitors of ovarian cancer in TISIDB." (PMID 36585688, 2022). "We demonstrated three potential biomarkers—CRABP2, SPP1, and TNFAIP6, which are higher in ovarian cancer and associated with poor prognosis." (PMID 35578123, 2022). "We observed that dendritic cell infiltration (p = 0.039) and SPP1 expression (p = 0.024) were significantly related to the prognosis of ovarian cancer." (PMID 36585688, 2022). "And in patients with recurrent ovarian cancer, the expression of SPP1 increased in the early stage, which can detect cancer recurrence earlier than that of CA125 alone." (PMID 34736480, 2021). "In a study about ovarian cancer, SPP1 was found to be overexpressed in ovarian cancer tissues and promote ovarian cancer progression." (PMID 31921672, 2019). "Notably, dendritic cell infiltration and SPP1 expression are key factors in ovarian cancer prognosis." (PMID 41391064, 2025). "Later research explored SPP1’s specific mechanisms in ovarian cancer." (PMID 41391064, 2025). "However, among the overlapped DE genes, we identified upregulation of genes encoding several markers typically overexpressed in ovarian cancer: cyclin E1 (Ccne1), RAD51-associated protein 1 (Rad51ap1), osteopontin (Spp1) and its signaling receptor, Cd44." (PMID 40642792, 2025). "This study investigated three key genes in ovarian cancer (OV), namely, SPP1, SLPI, and CD9." (PMID 40196737, 2025). "Subsequently, the survival and immune infiltration analysis demonstrated that the upregulation of five candidate genes, ITGB2, VEGFA, CLDN4, OCLN, and SPP1, were correlated with an unfavorable clinical outcome and increased immune cell infiltration in ovarian cancer." (PMID 36980477, 2023). "The expression level of SPP1 in ovarian cancer cells was significantly higher than that in normal ovarian cells, and the ability to promote apoptosis after knocking down SPP1 in ovarian cancer cells could be seen by flow cytometry." (PMID 37143732, 2023). "The results showed that knockdown of SPP1 significantly promoted apoptosis in ovarian cancer cells." (PMID 37143732, 2023). "Finally, we verified in vitro that SPP1 expression was significantly higher in ovarian cancer cells than in normal ovarian cells." (PMID 37143732, 2023). "By flow cytometry, we analyzed the function of SPP1 in ovarian cancer." (PMID 37143732, 2023). "Previous data have also highlighted the critical role of SPP1 in ovarian cancer." (PMID 36585688, 2022). "We next observed that SPP1 expression was positively related with immune-checkpoint, such as CD274, CTLA-4, LAG3 and TIGIT, suggesting that SPP1 may play an important role in immune tolerance of ovarian cancer." (PMID 36585688, 2022).
ovarian carcinoma (continued). "Furthermore, SPP1 expression level showed strong correlation with diverse immune cells in ovarian cancer." (PMID 36585688, 2022). "Secreted phosphoprotein 1 (SPP1) plays a vital role in tumor progression of multiple cancer types However, it still awaits further exploration whether SPP1 is a bystander or an actual player in the modulation of immune infiltration in ovarian cancer." (PMID 36585688, 2022). "Zeng found that SPP1 promotes ovarian cancer progression via Integrin β1/FAK/AKT signaling pathway." (PMID 35126478, 2022). "Previous studies have also highlighted the critical role of SPP1 in ovarian cancer." (PMID 36585688, 2022). "Our result agrees with the previous conclusion that SPP1 functions as an oncogenic gene and could help in the detection of early ovarian cancer solely or in combination with CA125." (PMID 35578123, 2022). "It showed that SPP1 could promote ovarian cancer growth by activating the AKT signaling pathway in nude mice model." (PMID 36585688, 2022). "The results showed that SPP1 was significantly overexpressed in ovarian carcinoma." (PMID 36585688, 2022). "SPP1 functions as a proverbial secretory protein that exerts pro‐tumor functions.[25a] To investigate the role of SPP1 in OC progression and metastasis, we showed that SPP1 knockdown reduced vascular permeability and impeded the migration, invasion, and proliferation of ovarian cancer cells." (PMID 39921309, 2025). "The ROC analysis revealed that both MEOX1 (AUC = 0.887, Confidence interval (CI) = 0.849 - 0.926) and SPP1 (AUC = 0.988, CI = 0.979 - 0.997) expression could serve as single significant parameters for discriminating between normal and tumor tissues of ovarian cancer (Figure." (PMID 38486335, 2024). "Thus, SPP1 expression may both be related to the metastasis mechanism and tumor microenvironment and may have a role in immunotherapies in ovarian cancer treatment." (PMID 38534733, 2024). "Notably, elevated SPP1 expression is positively associated with increased infiltration of various immune cells, including CD4+ T cells, CD8+ T cells, macrophages, neutrophils, and dendritic cells, suggesting that SPP1 plays a significant role in shaping the immune environment of ovarian cancer." (PMID 39727934, 2024). "SPP1 may be a potential therapeutic target for ovarian cancer." (PMID 37143732, 2023). "By flow cytometry, knockdown of SPP1 in ovarian cancer cells could promote tumorigenic apoptosis." (PMID 37143732, 2023). "Therefore, we selected SPP1 for further study in ovarian cancer." (PMID 37143732, 2023). "More specifically, we found that patients who had higher SPP1 expression levels showed a lower response to cisplatin-based chemotherapy, which is also supported by previous evidence from the literature and research on other types of cancers, such as lung and ovarian cancer." (PMID 35884419, 2022). "In conclusion, SPP1 might be an important regulator of tumor immune cell infiltration and act as a promising prognostic biomarker for ovarian cancer patients, offering a new probable immunotherapeutic target in ovarian cancer." (PMID 36585688, 2022). "Additionally, SPP1 expression regulation can promote cell growth and mobility in ovarian cancer, and this course may has the relation with the β1/FAK/AKT pathway." (PMID 33954053, 2021). "Additionally, the regulation of SPP1 expression influenced ovarian cancer both in vitro and in vivo, and this process may be related to the β1/FAK/AKT pathway (Zeng, Zhou, Wu, & Xiong, 2018)." (PMID 31304688, 2019). "The study comprehensively investigates the roles of SPP1, SLPI, and CD9 in ovarian cancer, providing insights into their functions in skeletal development, immune regulation, and tumor progression." (PMID 40196737, 2025). "Therefore, SPP1 may be a potential therapeutic target for ovarian cancer." (PMID 37143732, 2023). "Immunohistochemical analysis of selected (EPHA7, IFI-16, SPP1 and TGFBI) proteins was tested in ovarian cancer patients." (PMID 28611294, 2017).
ovarian carcinoma (continued). "The expression of EPHA7, IFI16, SPP1 and TGFBI was confirmed at protein level in analyzed ovarian cancer patients.." (PMID 28611294, 2017). "In ovarian cancer, all of the up-regulated genes were increased with more advanced stage (CXCL10, RIPK2 and SPP1) or higher pathological grade (CXCL11, KPNA2, RSAD2, THOC4 and TNC)." (PMID 23536776, 2013). "SPP1, SLPI, and CD9 and their mechanisms of action may be potential targets for the treatment of ovarian cancer with succinic acid." (PMID 40196737, 2025). "Moreover, we analyzed the Cancer Genome Atlas Ovarian Cancer (TCGA-OV) database, and found CD68+YAP1low groups exhibited dramatically increased M2-like TAMs markers expression, such as MMP9, CCL8, SPP1 and CCL17, when compared to CD68+ YAP1high." (PMID 39198883, 2024). "Similarly, SPP1 is positively correlated with CD8 + cells, CD4 + cells, macrophages, neutrophils, and DCs in ovarian cancer." (PMID 38919629, 2024). "Evidence showed that SPP1 could activate the AKT signaling pathway, and promote ovarian cancer growth in nude mice model." (PMID 36585688, 2022). "In addition, SPP1 was found to be overexpressed in many tumors, including GBM and ovarian cancer; therefore, the specificity of SPP1 as a biomarker of PDAC remains to be explored." (PMID 36292645, 2022). "However, the molecular mechanisms of SPP1 by modulating immune infiltration cell and prognosis of ovarian cancer were still not fully elucidated." (PMID 36585688, 2022). "Several genes found in our analysis have previously been described as biomarkers of ovarian cancer or potential therapeutic targets, including genes from the ITGA and ITGB superfamily, laminins, fibroblast growth factors, collagens, insulin growth factors, EGFR, FN1, EPHA2, TNC, SPP1, and VTN." (PMID 36352420, 2022). "Thus, the scoring model based on the gene expressions of CXCL13, IDO1, PI3, SPP1 and TRIM22 from GSE15622 dataset and constructed by lasso algorithm could better predict the sensitivity of ovarian cancer patients to chemotherapeutic drugs than which based on single gene." (PMID 34736480, 2021).
diabetes (87 papers, 2010 to 2025). "SPP1 has been linked to an increased risk of long-term effects of diabetes and has been found to be elevated in T2D patients." (PMID 35889263, 2022). "Together, our findings suggest that metformin might reduce the risk of dementia in diabetes patients through mechanisms beyond glycemic control, and that SPP1 is a candidate biomarker for metformin’s action in the brain." (PMID 36496454, 2022). "In this real-time fluorescence quantitative PCR experiment, there was also a clear and statistically significant high expression of SPP1 in the diabetes combined with MASLD group compared to the control group." (PMID 38886539, 2024). "SPP1 can also be traced in metabolic syndrome (MetS) through its role in conditions such as diabetes, non-alcoholic fatty liver disease (NAFLD), and hypertension." (PMID 38809924, 2024). "In summary, the candidate genes SPP1 and collagen IV screened based on bioinformatics analysis have the potential to influence the course of type 2 diabetes mellitus combined with MASLD." (PMID 38886539, 2024). "Our data showed a ~2-fold increase in SPP1 expression on the ocular surface in the HFD + STZ group at 4 weeks post-diabetes induction, compared to both WT normal and HFD-fed mice, a trend that persisted through 16 weeks (P < 0.01)." (PMID 39480896, 2024). "A total of two target genes (SPP1, collagen IV) were found to be highly correlated with type 2 diabetes mellitus combined with MASLD." (PMID 38886539, 2024). "Spp1 is reported to be involved in angiogenesis, including post-myocardial ischemic neovascularization, peripheral artery disease and diabetes mellitus, and AMD." (PMID 36675807, 2023). "SPP1, also known as phosphoprotein 1, is a glycoprotein involved in the immune and inflammatory responses, playing an active role in the development of diabetes, fatty liver disease, and cancer." (PMID 37755786, 2023). "SPP1, also known as osteopontin (OPN), is a key regulator of tumor progression and immunomodulation involved in multiple pathologies such as cardiovascular, diabetes, kidney, proinflammatory, fibrosis, nephrolithiasis, wound healing, and cancer." (PMID 36139385, 2022). "In our current study, we found that: SPP1, collagen IV may be considered as potential candidate targets for the treatment of diabetes combined with MASLD." (PMID 38886539, 2024). "Additionally, elevated SPP1 levels contribute to the progression of diabetes through beta-cell apoptosis." (PMID 38809924, 2024). "In this study we found that SPP1 is involved in diabetes combined with MASLD." (PMID 38886539, 2024). "SPP1 and Collagen IV may be candidate biomarkers for type 2 diabetes mellitus combined with MASLD, as verified by bioinformatics screening and in vitro experiments." (PMID 38886539, 2024). "Some studies have explored the effect of anti-hypertensive, anti-diabetes, and statin drugs on Alzheimer’s disease and found that they may lead to a relative reduction in SPP1 levels." (PMID 38809924, 2024). "Interestingly, secreted phosphoprotein 1 (SPP1) appeared in both diabetes-like conditions as one of the top changed candidates." (PMID 34046254, 2021). "Since the hyperglycemic hyperosmolar state is a serious acute metabolic complication of diabetes mellitus, further experiments should unravel potential relations of hyperglycemic and osmotic conditions that induce decrease in SPP1 levels." (PMID 34046254, 2021). "However, with increasing age and progression of diabetes, both gene and protein levels of SPP1/OPN increased markedly, confirming previous reports." (PMID 39480896, 2024). "Furthermore, SPP1 was identified to be highly down regulated in the VAT after WE consumption and should be further explored as it relates to outcomes of WE consumption and Diabetes." (PMID 34041258, 2021).
gastric cancer (86 papers, 2007 to 2025). A primary or metastatic malignant neoplasm involving the stomach. "Marked infiltration of SPP1-expressing TAMs correlated with a worse clinical course in gastric cancer, the SPP1/CD44 axis potentially associated with stemness properties, and intratumoral heterogeneity linked to resistance to anticancer therapies." (PMID 37190178, 2023). "In the present study, we demonstrated that SPP1 was widely upregulated in multiple cancerous tissues, including GC, and it was associated with advanced gastric cancer stages (AJCC TNM stage III–IV)." (PMID 36612160, 2022). "Previous study showed overexpression of SPP1 (secreted phosphoprotein 1) in gastric cancers and its association with cancer progression." (PMID 25860484, 2015). "In addition, in a recent study, SPP1 rs4754 polymorphism was observed to be associated with the risk of gastric cancer and has an important effect in gastric carcinogenesis." (PMID 34126961, 2021). "SPP1 was associated with tumor metastasis in gastric cancer and esophageal adenocarcinoma." (PMID 31850052, 2019). "Among these, SPP1+ macrophages have emerged as a particularly important population in gastric cancer, CRC, and HCC." (PMID 41316282, 2025). "Our study has identified a potential stromal immunosuppressive barrier in gastric cancer, characterized by the presence of Macro_SPP1/C1QC macrophages and CD8_Tex_C1 T cells." (PMID 40740771, 2025). "In the liver metastasis model, we successfully observed GDF15 + SPP1 + TAMs and significantly inhibited the liver metastasis ability of gastric cancer after using GDF15 blockade." (PMID 38365757, 2024). "Most recently, Helicobacter pylori infection-induced SPP1 activation was found to promote chemoresistance and T cell inactivation in gastric cancer cells." (PMID 39409192, 2024). "Other studies have reported that SPP1 + /C1QC + and SPP1 + /C1QC-, SPP1-/C1QC + macrophage subtypes coexist in gastric cancer." (PMID 38365757, 2024). "The study found that the immunosuppressive microenvironment of gastric cancer is dynamically related to the emergence of SPP1 + TAMs during anti-PD-1 immunotherapy." (PMID 38365757, 2024). "The high HOXC8/high SPP1 group was associated with shorter overall survival than the low HOXC8/low SPP1 group was among gastric cancer patients." (PMID 37670969, 2023). "Our study further validated that down-regulating SPP1 markedly curtailed the proliferation and migration capacities of gastric cancer cells, underscoring its potential as a therapeutic target." (PMID 37889539, 2023). "In gastric cancer cell lines, the elevated expression of SPP1 was a critical determinant of poor prognosis." (PMID 37097499, 2023). "In three cancer types (i.e., anaplastic thyroid, colorectal, and gastric cancers), mIF consistently illustrated the proximity of some SPP1+ TAMs (SPP1+CD68+) to CAFEndMT (CD44+CD31+)." (PMID 36333338, 2022). "Studies have shown that SPP1 plays an important role in the progression of certain tumors, but the specific functional mechanism in gastric cancer (GC) is still unclear." (PMID 36612160, 2022). "SPP1 rs4754 genotype interacts with SPARC SNPs, rs1054204, rs3210714, and rs3549, via epistatic mechanisms that increases the risk of the development of gastric cancer." (PMID 34209679, 2021). "In summary, our results demonstrate that type I collagen is capable of promoting the TIC phenotype in gastric cancer cells via the ITGB1/YBX1/SPP1/NF-κB signaling pathway." (PMID 34758833, 2021). "A study based on gastric cancer cell lines indicated that the elevated expression of SPP1 is a critical determinant of poor prognosis." (PMID 34126961, 2021). "To further confirm the role of YBX1 and SPP1 in gastric cancer development, we assessed overall survival in gastric cancer patients with low/high expression of YBX1 and SPP1 using TCGA database analysis." (PMID 34758833, 2021).